IL6 (interleukin 6)
Diseases named in the same sentence as IL6 in open-access papers (continued):
Sharing a sentence is not in itself a finding about the gene and the disease.
fungal infection (continued). "Plasma levels of IL-6 were shown to be significantly elevated in patients suffering from a fungal infection in comparison to septic patients with a fungal colonization or without any fungal findings at different time points especially in the early course of the disease (e.g., at T0, T1)." (PMID 28820494, 2017). "KLF4 may influence the Th1/Th2 balancing via IL6 and thereby be a key regulator in fungal infections." (PMID 27346433, 2016). "In addition, knocking down c-Jun and c-Fos in macrophages decreases H. capsulatum-induced TNF and IL-6 response, highlighting the role of AP-1 in host defense against fungal infections." (PMID 26132276, 2015). "Obese and overweight patients may have had less aggressive disease, as shown by our evaluations of blunted host inflammatory response to pathogens (lower IL-6), and an altered pattern of infection (less frequent lung and fungal infection)." (PMID 23786836, 2013). "As we previously showed that Dectin-1 mediates neutrophil recruitment into the cornea during Aspergillus infection, and IL-6 is known to mediate hepatic hepcidin production, we examined the role of Dectin-1 and IL-6 in iron-sequestration during fungal infection." (PMID 23853581, 2013). "Notably, during the treatment course, the patient’s IL-6 level surged to a peak of 181.5 pg/mL (normal range: 0–7 pg/mL)—a change that directly coincided with the progression of infection: the initial ear fungal infection extended to a secondary pulmonary fungal infection." (PMID 41394144, 2025). "Additionally, with fungal infection, there were significant differences between the patient groups and control group (p = 0.002, 0.01) in the genotypes (GG, GA, and AA) of IL-17A and the genotypes (CC, CG, and GG) of IL-6 G-174C.correspondingly." (PMID 39289412, 2024). "Nevertheless, as in mammals, it is possible that the IL-1-β, IL-6 and IL-15-like proteins may play an important role in fungal infection, as their levels increased in infected insects; however, a better understanding of the role of these proteins during infection is needed." (PMID 38774871, 2024). "However, when IL-8 and IL-6 are elevated simultaneously, it may indicate that the patient has a bacterial and fungal infection." (PMID 36319826, 2022). "However, IL-6-deficient mice fail to mount TH1-cell responses to bacterial and fungal infections." (PMID 30169526, 2018). "In our group, we could recently demonstrate a similar effect in monocytes upon fungal infection, reporting the down-regulation of Candida albicans-induced TNFα, IL-6 and IL-12B expression in response to all-trans retinoic acid (atRA), the active metabolite of vitamin A21." (PMID 28094291, 2017). "In addition, severe COVID-19 causes an increase in proinflammatory mediators, such as IL-1, IL-6, and tumor necrosis factor-alpha (TNF-α), less CD4 interferon-gamma (INF-γ) expression, and fewer CD4 and CD8 cells, which enhance susceptibility to both bacterial and fungal infections inside the body." (PMID 36992139, 2023). "There were significant differences in IL-4, IL-6, IL-8, IL-10, IL-12p70, IL-1β, IL-2, TNF-β, IL-17, and IL-22 between the uninfected group and the pulmonary bacterial and fungal infection group (P < 0.05)." (PMID 36319826, 2022). "There were significant differences in IL-6, IL-8, IL-10, IL-12p70, and TNF-β between the pulmonary bacterial infection group and the pulmonary bacterial, fungal infection group (P < 0.05)." (PMID 36319826, 2022). "On the other hand, we believe that if anticytokine treatment targeting IL-6 or IL-1 will be used later, very high doses of CCS should be avoided to reduce potential complications of secondary opportunistic bacterial or fungal infections." (PMID 34803441, 2021). "In the case of fungal infections, the outcome partly depends on the Th1 protective cellular response, which is principally driven by the proinflammatory cytokines TNF, IFN, IL-6, IL-12, and IL-1." (PMID 31484389, 2019).
fungal infection (continued). "Toll-like receptors (TLR2, TLR4), pro-inflammatory cytokines [tumor necrosis factor, interleukin 6 (IL-6), IL-1, and interferons], nuclear factor κB signaling, and HMGB1 were among top upstream regulators of the targets in fungal infection." (PMID 31969817, 2019). "Taken together, this data demonstrate that MCs can respond to fungal infections by tightly interacting with C. albicans hyphae and releasing pro-inflammatory mediators as TNF-α and IL-6." (PMID 30555491, 2018). "Since monocytes represent a major source of pro-inflammatory cytokines such as TNF-α or IL-6 during infection, this may explain the prolonged pro-inflammatory response and sustained inflammation in organs such as brain, lung and eye in neonates suffering from bacterial or fungal infection." (PMID 27870876, 2016). "IL‐6 is a pleiotropic cytokine that signals through STAT3 and is evidently critical in protection against staphylococcal and fungal infections." (PMID 27957331, 2016). "This suggests that the corneal epithelial cells can express more IL-1β, IL-6, IL-8 and CXCL1 after identifying the fungus, which resist the fungal infection and induce inflammatory cells infiltration to remove pathogenic fungi." (PMID 26036769, 2015). "To determine if fungal infection of the cornea initiates an iron-sequestration response, we infected C57BL/6, Dectin-1−/−, and IL-6−/− mice intrastromally with A. fumigatus dsRed conidia as described." (PMID 23853581, 2013). "During fungal infections, various pro-inflammatory cytokines such as TNF, IL-12p70, IL-23 and IL-6, produced by the activated leukocytes, result in the promotion of a sustained Th1 and Th17 response." (PMID 23675302, 2013). "Th17 cells can directly activate the local immune response by secreting cytokines, such as IL-17A and IL-17F, which promote the production of various inflammatory mediators (such as IL-6 and TNF-α), thus increasing the intensity of the inflammatory response against bacterial or fungal infections." (PMID 39794999, 2024). "Our study also found that after fungal infection, Dectin-1 affected the expression levels of phenotype-related factors (TNF-α, INOS, IL-6, IL-12, Arg-1, or IL-10) in M1 and M2-type macrophages through the regulation of MAPK signaling pathways, such as p38, JNK, and ERK." (PMID 39478855, 2024). "C. neoformans also induces the production of other cytokines, such as IL-6, IL-1α, IL-1β, and type I interferon (IFN-I) from innate immune cells, of which IL-6 can induce the activation of STAT3 phosphorylation, which plays a crucial role in acute/chronic inflammation and fungal infection." (PMID 37251371, 2023). "Th17 cells play an important role in the host defense against fungal infections, such as candidiasis, by stimulating the production of other cytokines, such as TNF-α, IL-6, and IL-1β, and enhancing the recruitment and activation of neutrophils, which are essential for killing Candida cells." (PMID 38003833, 2023). "Leukocyte, neutrophil, monocyte, PCT and IL-6 were not significantly different between the fungal and non-fungal infection groups." (PMID 36237437, 2022). "C-type lectins receptors were shown to recognize fungal cell wall β-glucan and mannan, activate downstream signaling pathways, promote immune cells to secrete IFN-γ, IL-6, TNF-α, and other pro-inflammatory cytokines, and initiate adaptive immune responses to clear fungal infection." (PMID 36079904, 2022). "The absence of neutrophils leads to a better clearance of the fungal infection, followed by higher IL-6 production in the spleen and liver after the first 48 h of infection." (PMID 34642440, 2021). "IL-22 typically protects against bacterial and fungal infections, but recent findings suggest that it amplifies the effects of other cytokines that are known to be involved in ocular inflammation, such as interleukin 1-β (IL-1β), tumor necrosis factor-α (TNF-α), interleukin 6 (IL-6), and IL-17." (PMID 38247834, 2024).
fungal infection (continued). "The few reported cases could be an indicator of the relative safety of TCZ in that type of infection, irrespective of the role of the IL-6 signaling pathway in fungal infections, implying the involvement of alternative pathogenetic pathways." (PMID 37367619, 2023). "Tocilizumab, another IL-6 antibody, was found to be safe, but it showed an increase in the incidence of adverse infectious events such as bacterial and fungal infections with no better outcomes with 400 mg dose compared with patients treated with a single dose of tocilizumab 400 mg." (PMID 34721573, 2021). "We used a concentration of half the MIC value of each drug to examine its possible effects on cytokine secretion and fungal SOD activity; the results showed that there was no change in the levels of IL-6 and IL-8 in antifungal-treated macrophages within 28 hours after fungal infection." (PMID 33680221, 2021). "IL-6 and IL-8 levels are elevated not just in children with hematological malignancies, but also when there is an invasive fungal infection of the lungs in children with hematological malignancies and may signal the patients’ early death." (PMID 34925324, 2021). "IL-17 can stimulate the generation of various cytokines (such as TNF and IL-6), vascular endothelial growth factor (VEGF), and chemokines (CXCL1 and CXCL8), increase AMP expression, and promote keratinocyte proliferation, which may essentially lead to the clearance of cutaneous fungal infection." (PMID 38022599, 2023). "The levels of IL-6, IL-8, and IL-10 in CML patients with bacterial and fungal infections of the lung were significantly higher than those without infection." (PMID 37114211, 2023). "Additionally, M1‐type cytokines, such as IL‐4, IL‐12, IL‐6, IL‐23, TNF‐α, IL‐1β, and IFN‐β, were slightly elevated upon stimulation by fungi, but no statistical difference was detected between the two fungal infection groups." (PMID 37211685, 2023). "The responses of IL-6 and TNF-β consist of up-regulation in the presence of C. albicans, but this is not specific to SOCS1 silencing, suggesting that these cytokines are not regulated by the SOCS1 gene in fungal infections." (PMID 25381480, 2015). "The decrease of proinflammatory cytokines could be associated with a reduction of infection and absence of hyphae, once the marked release of IL-6 occurs due to the exposition of hyphal fragments of A. fumigatus TNF plays an important role in host immune defense against invasive fungal infections." (PMID 34249777, 2021).
brain injury (99 papers, 2006 to 2026). Acute and chronic (see also brain INJURIES, CHRONIC) injuries to the brain, including the cerebral hemispheres, CEREBELLUM, and brain STEM. "A potential diagnostic aid is that of biomarkers, such as IL-6, as they can monitor the progression of concussions and the efficacy of treatment methods used." (PMID 38505457, 2024). "In various in vitro experiment models, inflammatory factors, such as TNF-α, IL-1β, and IL-6, have been shown to be associated with CI-induced brain injury." (PMID 34867377, 2021). "IL-6 is observed to be acutely increased following mTBI in emergency room patients and also significantly discriminated athletes with concussion from controls within 6 h of injury and was associated with post-concussive symptoms after injury." (PMID 32508732, 2020). "In one study, elevated IL-6 serum levels within the first 17 h following severe brain injury effectively identified patients at risk of developing problematic levels of ICP." (PMID 30202571, 2017). "It is known that neutral SMase participates in IL-6 release in mouse neuronal cultures through the activation of the neutral SMase/Src kinase signaling pathway, effects that can be associated with acute brain injury." (PMID 34445139, 2021). "In sum, any interpretations are speculative, and the underlying mechanisms tying IL-6 to concussion pathophysiology require future investigation." (PMID 32343752, 2020). "It is also suggested that IL-6 is involved in the repair of the consequences of traumatic brain injuries and in cognitive dysfunction." (PMID 40646278, 2025). "Visser K demonstrated that as a result of inflammatory responses after mTBI, interleukin-6 was the most promising biomarker for clinical diagnosis of brain injury, while interleukin-10 was a potential candidate for CT scan triage." (PMID 40881786, 2025). "In the case of acute brain injury, elevated levels of cf-mtDNA correlated with clinical severity and interleukin-6 (IL-6) cytokine response were found in CSF and serum samples." (PMID 40080233, 2025). "These activated cells subsequently release large amounts of inflammatory mediators, such as TNF-α, interleukin-1β (IL-1β), and interleukin-6 (IL-6), aggravating brain injury." (PMID 40724973, 2025). "It was shown that OX-A significantly improves the outcome of mice with ischemic brain injury by reducing inflammation through the modulation of Interleukin-6 (IL-6) and tumor necrosis factor α (TNF-α) in microglia." (PMID 40149526, 2025). "In a traumatic brain injury model, ∆9-tetrahydrocannabinol treatment impaired motor function and increased levels of cytokine interleukin-6 in males only, thus suggesting sex-specific cannabinoid effects." (PMID 38338884, 2024). "Inflammatory mediators (IL-6, IL-12p40, HGF, M-CSF, CCL2, and IL-1RA) are associated with both altered consciousness and markers of brain injury." (PMID 38135686, 2023). "Previous studies also show that cooling is accompanied by a reduction in TNF-α, IL-6, and IL-1β expressions in the setting of ischemic brain injury and neuroinflammation." (PMID 34776788, 2021). "That is, TLR4 and C5aR1 represent an alternative upstream regulator in activating NF-κB by inhibiting cAMP/PKA signals and participate in TNF-α, IL-1β, and IL-6 production in MCAO/R-induced brain injury." (PMID 33633530, 2021). "The purpose of this study was to examine the blood concentrations of IL-6 in response to sport-related concussion while addressing the potential confounds of sex, recent physical activity, and the interacting effect of concussion history." (PMID 32343752, 2020). "Inflammatory cytokines (IL-6, IL-10, and TNFα) were measured acutely in blood samples within 8 h following a medically diagnosed concussion and then 24 h later." (PMID 32450801, 2020). "Brain ECF (extracellular fluid) detection of raised parenchymal IL-6 levels, using microdialysis, has been correlated with improved survival in brain injury patients." (PMID 33143727, 2020).
brain injury (continued). "Considering these early findings in concussion, additional studies with longer follow up are warranted to understand the role of IL-6 in recovery and links to long-term consequences." (PMID 32450801, 2020). "Pro-inflammatory cytokines, such as TNF-α, IL-1β, and IL-6, are produced in the central nervous system and exert great effects on neuroprotection, which have been proven to be elevated in traumatic brain injury." (PMID 33791290, 2020). "Elevated brain protein levels of TNF-α, IL-1β and IL-6 have also been detected in human CSF and serum after brain injuries." (PMID 30682785, 2019). "There is substantial evidence that pro-inflammatory cytokines, TNF-α, IL-1β and IL-6 can operate at very low concentrations on many cell types in the CNS or periphery, and can contribute to neurodegeneration in acute brain injury." (PMID 30682785, 2019). "Many studies have demonstrated the neuroprotective effects of IL-6 in ischemic brain injuries, although few studies suggest that IL-6 has an injurious effect." (PMID 29921762, 2018). "In patients with severe brain trauma and brain death, a large amount of IL-6 is released into the circulation." (PMID 28332628, 2017). "The main cytokines associated with inflammation in ischemic brain injury are IL-1, TNF-α, IL-6, IL-10 and TGF-β and have been observed to be upregulated in ischemic brain injury." (PMID 25815894, 2015). "IL-6 contributes to tissue repair after ischemic brain injury and IL-23 exerts neurotoxic effects during early-phase IS, while the loss of IL-1β function reduces infarct size." (PMID 24991091, 2014). "Electrical VNS against a burn injury model reduced serum levels of TNF-α and IL-6, and in a traumatic brain injury model, the suppressive effect of VNS on TNF-α was shown in intestine." (PMID 23424673, 2013). "Previous studies also reported elevated levels of inflammatory markers in blood following brain trauma, including IL-1, IL-6, IL-8, TNF-α and furthers." (PMID 23894384, 2013). "In patients with brain injury, jugular IL-6 levels were higher than its arterial levels, suggesting that IL-6 had originated from the brain." (PMID 25013647, 2013). "In patients with cerebral edema attributable to brain trauma, the inflammatory reaction and some pro-inflammatory cytokines, such as IL-6 and IL-8, can be detected." (PMID 24223711, 2013). "Similarly, serum levels of IL-6 were found to correlate with clinical symptomseverity after a sports-related concussion, as it remained elevated at 14 dayspost-injury." (PMID 40666430, 2025). "Although studies on repetitive head impacts are lacking, previous studies have found associations with IL-6 and IL-8 and traumatic brain injury." (PMID 41264095, 2025). "Tau also reduces TNF-α and IL-6, alleviating the severity of brain injuries." (PMID 39457890, 2024). "IL-6 has been shown to stimulate brain repair by microglia particularly in traumatic brain injury." (PMID 39334365, 2024). "This ACh subsequently acts on α-7 nicotinic acetylcholine receptors (α-7nAChR), predominantly expressed on macrophages, leading to a reduction in pro-inflammatory cytokines such as TNF-α, IL-1β, and IL-6, thereby facilitating the recovery of neurological function following acute brain injury." (PMID 39723424, 2024). "IL-6 is one of the most important cytokines whose release increases during a brain injury." (PMID 36831126, 2023). "In a murine model of ischemic brain injury, IL-6 was noted to help decrease BBB integrity." (PMID 37841263, 2023). "In sports related concussion IL-6 levels correlated with symptom burden in young adults." (PMID 35130911, 2022). "Indeed, the levels of proinflammatory cytokines such as TNF-α, IL-1β, and IL-6 were significantly elevated in the early stage after brain injuries." (PMID 35163096, 2022). "The rise in IL-6 level may support the possible role of this cytokine in the pathogenesis of hypoxic-ischemic brain injury." (PMID 34282369, 2021).